INS (insulin)
Diseases named in the same sentence as INS in open-access papers (continued):
Sharing a sentence is not in itself a finding about the gene and the disease.
type 2 diabetes (continued). "Most of the data from the insulin signaling models comes from isolated primary adipocytes from non-diabetic and type 2 diabetic patients, where protein levels and activities have been measured using antibodies and the western blot technique." (PMID 37286693, 2023). "Interventions to reduce iron excess, such as via venesection or the use of chelators, have been shown to improve insulin sensitivity and delay the onset of type 2 diabetes and heart failure, although this approach has not always been successful." (PMID 36901833, 2023). "The INTERFAST (Intermittent Fasting)–2 trial evaluated the efficacy and safety of intermittent fasting for patients with insulin-treated type 2 diabetes and showed that ADF for 12 weeks improved HbA1c, reduced body weight, and led to a total daily decrease in insulin dose." (PMID 38002621, 2023). "PIO is often used in combination with other medications such as sulfonylurea, metformin, or insulin to help achieve optimal glycemic control in people with type 2 diabetes who have not been able to achieve adequate blood glucose control with monotherapy alone." (PMID 37446573, 2023). "Type 2 diabetes (T2D) is a metabolic disorder characterized by a relative lack of insulin secretion by pancreatic β cells, which interferes the adipocyte lipolysis, skeletal muscle glucose uptake, and glucose metabolism in liver." (PMID 37111724, 2023). "While there is no preventive measure for type 1 diabetes, treatment is applied for type 2 diabetes using insulin or noninsulin medication drugs." (PMID 37048331, 2023). "In adults with type 2 diabetes, the benefits of fully closed-loop insulin delivery, which does not require meal bolusing, are unclear." (PMID 36631592, 2023). "Hepatic extraction, insulin secretion rates and glucagon secretion rates in people with and without type 2 diabetes." (PMID 37751301, 2023). "The Goto-Kakizaki (GK) rat is a polygenic model of Type II diabetes that is neither obese nor insulin dependent." (PMID 37034167, 2023). "Finally, we observed that proinsulin/insulin area ratio progressively increased in pancreatic islets from NGT to type 2 diabetes (p=0.03) (NGT=0.5; IGT=1.6; type 2 diabetes=3.3 [proinsulin/insulin area ratio mean values])." (PMID 36280617, 2023). "Clinical trials assessing the 3-month (and greater) outcomes on insulin sensitivity in overweight/obese individuals with or without type 2 diabetes." (PMID 37396181, 2023). "The results also showed no significant reduction in key type 2 diabetes-related indicators (glycated hemoglobin, fasting glucose, fasting insulin, and insulin resistance index)." (PMID 36970527, 2023). "Hearts from AT-001-treated mice with type 2 diabetes exhibited reductions in palmitate oxidation rates with no change in glucose oxidation rates in the absence or presence of insulin." (PMID 36978133, 2023). "In type 2 diabetes, the body quits replying to normal insulin levels, and over time, the pancreas does not produce enough insulin to sustain the body’s needs." (PMID 37765234, 2023). "According to the available guidelines, insulin or insulin analogs should be administered when the target blood glucose level in patients with type 2 diabetes is not achieved." (PMID 37324170, 2023). "Continuous glucose monitoring (CGM) is recommended for many people with diabetes, including those with type 1 diabetes, type 2 diabetes treated with insulin, and type 2 diabetes treated with noninsulin regimens." (PMID 37093632, 2023). "Experiments in mice suggest that decreased GRP78 expression in the liver may induce resistance to insulin by inhibiting AKT activation and may play an important role in the development of type 2 diabetes." (PMID 37569434, 2023). "Given that intranasal insulin bypasses the BBB to enter the brain with negligible systemic consequences, there has been much interest in the use of intranasal insulin to treat individuals with cognitive decline, obesity/type 2 diabetes and mood disorders." (PMID 36979453, 2023).
type 2 diabetes (continued). "Type II diabetes is the more common form of the disease and develops when the body becomes resistant to insulin or does not produce enough insulin to regulate blood sugar levels." (PMID 37892742, 2023). "Another proposed subtype is a phenotype like “decompensated” type 2 diabetes, which presents with a high A1c and detectable C-peptide, but new insulin dependency with or without prior history of type 2 diabetes." (PMID 37671166, 2023). "There were no RCTs on the incidence of type 2 diabetes, so surrogate measures (glucose tolerance, insulin sensitivity) were reported." (PMID 38084156, 2023). "Their results showed that MGE benefits type 2 diabetic mice, including by lowering their FBG and increasing the serum insulin, inhibiting gluconeogenesis and insulin resistance, enhancing hepatic fatty acid oxidation, improving blood lipids, and impairing hepatic AMPK and insulin signalling." (PMID 37048193, 2023). "Our results confirm that Wnt5a protein is closely related to pancreatic islet dysfunction in type 2 diabetes, and it may be a key protein for GLP-1RA to promote insulin secretion in beta cells." (PMID 37255814, 2023). "The large chronic epidemic known as type 2 diabetes (T2D) arises when the body fails to use insulin." (PMID 37175908, 2023). "Another study found that nighttime hypoglycemia in insulin-treated people with type 2 diabetes led to atrial fibrillation, bradycardia, and non-sustained ventricular tachycardia." (PMID 37887414, 2023). "Of these, 23 (35%) were identified as having type II diabetes without use of insulin, and five (7%) had C-peptide levels not indicative of insulin dependence." (PMID 37671166, 2023). "Type 2 diabetes mellitus is typically diagnosed based on the presence of elevated blood glucose levels that can be managed without the use of exogenous insulin." (PMID 37274075, 2023). "In people with type 2 diabetes, exendin 9-39 infusion did not significantly alter fasting insulin concentrations, nor those observed during the hyperglycemic clamp." (PMID 37751301, 2023). "In Type I diabetes, the pancreas is incapable of producing insulin, while in Type II diabetes, the pancreas does not produce enough insulin and/or the body becomes resistant to it." (PMID 37504117, 2023). "We aimed our current expert position to update the prior published algorithm on the most suitable choice of CGM for insulin-treated PwD in light of the recent evidence reporting the efficacy and safety of CGM in type 1 and type 2 diabetes, and clinical practice." (PMID 37676398, 2023). "Patients with early-onset type 2 diabetes are more likely to use insulin to lower blood sugar, regardless of initial intensive insulin therapy or as the disease progresses, with the decline of pancreatic β-cell function." (PMID 36864833, 2023). "in June 2019, the UK Medicines and Healthcare Products Regulatory Agency reported that DKA may occur in type 2 diabetes patients receiving combined GLP1 receptor agonists and insulin therapies when insulin is abruptly reduced or discontinued." (PMID 37335652, 2023). "Paradoxically, in type 2 diabetes, insulin fails to inhibit glucose production yet stimulates lipogenesis, hence the liver is selectively insulin resistant." (PMID 36920797, 2023). "The risks of fasting after MBS may be higher in the presence of obesity related medical problems such as type 2 diabetes (T2DM), hypertension (HTN) especially when patients are using certain medications like insulin and diuretics." (PMID 37980363, 2023). "In type 2 diabetes, this drug quickly corrects the disorder of meal-stimulated insulin secretion, without increasing the secretion of the hormone between meals and at night." (PMID 38276837, 2023). "Consistent with our results, DPP4 inhibitors and GLP‐1 analogs have not been found to significantly improve insulin sensitivity in patients with type 2 diabetes." (PMID 36585794, 2023).
type 2 diabetes (continued). "The result of this analysis indicates that use of MDMW is expected to be “dominant”over usual care (both cost saving and life improving), in supporting self-managementin people with type 2 diabetes not treated with insulin." (PMID 34986658, 2023). "Data from two interventional studies reported that daily supplementation of 900 mg raw propolis during 18 weeks had no beneficial effects on FBG, serum insulin and Hemoglobin A1c among patients with type 2 diabetes mellitus." (PMID 36932147, 2023). "This study will refer to the two major forms of diabetes: type 1 diabetes (T1D - insulin-dependent) and type 2 diabetes (T2D - non-insulin-dependent)." (PMID 37063529, 2023). "According to available reports, the development of type 2 diabetes can be summarized in two main points: insulin resistance and the destruction of pancreatic beta-cell function, resulting in the production of insulin that does not meet the body’s needs." (PMID 36986268, 2023). "Ultimately, the insulin/non-insulin dependent categories were retained but coded to type 1/type 2 diabetes as ‘best fit’." (PMID 37562854, 2023). "Here, we evaluate the impact of insulin and non-insulin therapy on glucose control in patients with type 2 diabetes admitted with COVID-19." (PMID 36701712, 2023). "Overall, despite their obesity, T-Rheb−/− mice did not exhibit a type 2 diabetes profile, but rather showed improved glucose tolerance and insulin sensitivity (even when challenged with an HFD)." (PMID 37358498, 2023). "In the study group, the most commonly diagnosed comorbidities were type 2 diabetes in 30 patients (insulin nondependence), hypertension in 9 patients, asthma in 5 patients, and thyroid diseases in 2 patients." (PMID 36624488, 2023). "Prediabetes is an intermediate metabolic condition that is characterized by reduced insulin sensitivity leading to temporary glucose excursions, but not yet as pronounced as in type 2 diabetes." (PMID 37258943, 2023). "This study aims to analyze, compare and describe admission parameters in patients with type 2 diabetes, obesity, and SARS-CoV-2 infection based on whether they received insulin therapy before hospital admission." (PMID 36983573, 2023). "More recently, studies in humans with type 2 diabetes have shown that low‐dose gliclazide, which does not stimulate insulin secretion at low glucose levels, augments insulin secretion in response to oral, but not intravenous, glucose." (PMID 37602910, 2023). "Treatments that reduce postprandial glycemia (PPG) independent of stimulating insulin secretion are appealing for the management of type 2 diabetes (T2D)." (PMID 36734166, 2023). "Nutritionally driven disbalance of the insulin–GH–IGF-I axis may be an important etiological factor in the development of metabolic syndrome, impaired glucose tolerance and type 2 diabetes." (PMID 36901984, 2023). "AAP and its in vitro hydrolysate could significantly improve the body weight and blood sugar changes of streptozotocin-induced type 2 diabetic rats, reduce TG and LDL-C levels, as well as promote insulin secretion and hepatic glycogen synthesis." (PMID 35407029, 2022). "Therefore, in the drug profile associated with CRG-5424, the most frequent ATC codes are ‘A10BA’ (biguanides for treating diabetes type-II), ‘C10AA’ (drug for preventing cardiovascular diseases) and ‘A10AE’ (insulin for treating diabetes type-I)." (PMID 36064616, 2022). "Then, Type 2 diabetes–it is a condition in which the insulin produced does not effectively used to maintain the blood sugar level in the body." (PMID 35433625, 2022). "Moreover, researchers proved the link concerning low clearance insulin levels and low hepatic IDE activity in people with obesity or type 2 diabetes." (PMID 36304965, 2022).
type 2 diabetes (continued). "A PubMed literature search retrieved 43 reported prospective clinical trials introducing basal insulin in 17643 insulin-naïve patients with type 2 diabetes reporting fasting plasma glucose (FPG), HbA1c, target achievement, hypoglycemic events, and insulin doses." (PMID 35942330, 2022). "In particular, the panel expressed the feeling that CGM can be prognostically relevant for every diabetic patient (70%) and that is clinically useful also in the management of those with type 2 diabetes not treated with insulin (87.5%)." (PMID 36030229, 2022). "This study provided statistically significant reduction of >5% body weight in contrast to placebo over 52 weeks in patients with type 2 diabetes poorly controlled with insulin with/without metformin." (PMID 36654602, 2022). "In total, 6 patients had type 2 diabetes with a good glycemic control (HbA1c < 7.5%); of these, one was treated only with metformin, two with metformin plus DPPIV inhibitor plus insulin secretagogue, and three with metformin plus DPPIV inhibitor plus insulin." (PMID 35407437, 2022). "Type 2 Diabetes (T2D) is characterized by insulin resistance, a condition in which the body does not respond appropriately to insulin." (PMID 35600583, 2022). "However, in the present study, we figured out that the insulin secretion level is similar in non-diabetic participants with different rs5219 genotypes, which is in line with the lack of association of this polymorphism with type 2 diabetes development across Iranian adults." (PMID 36456687, 2022). "Previous studies have demonstrated that both blinded and unblinded FGM can improve glycemic control in patients with type 2 diabetes (T2DM) compared with SMBG, and the main reason was that FGM guided the adjustment of insulin dosage or oral antidiabetic drugs in these patients." (PMID 35222287, 2022). "Type 2 diabetes is initially treated by increasing exercise and lifestyle changes; if blood sugar levels do not decrease, then medications such as metformin or insulin are needed." (PMID 36584077, 2022). "Because its glucose-lowering effect is not operated by either insulin secretion or insulin sensitivity, the concern for hypoglycemia is scarce by a sole administration of this agent for the treatment of type 2 diabetes (T2DM)." (PMID 36281369, 2022). "In patients with type 2 diabetes, the incidence of hepatic steatosis is higher and of insulin clearance is lower than nondiabetic subjects." (PMID 36009446, 2022). "It is often characterized by the favorable metabolic profile, which means that this type of obesity is not accompanied by common metabolic disorders such as type 2 diabetes, high blood pressure or insulin sensitivity." (PMID 35407559, 2022). "The pathogenesis of type 2 diabetes starts when peripheral organs, such as adipose tissue and muscle, become resistant to insulin and are no longer able to take up circulating glucose." (PMID 35802167, 2022). "A recent meta-analysis that included 20 randomized controlled trials found that oral vitamin D supplementation did not influence the FBS, HbA1c, and fasting insulin levels in type 2 diabetes." (PMID 35720377, 2022). "Therefore, due to the necrotic effects on pancreatic beta cells, which limit insulin release, HFD ZDF rats are commonly utilized as models for type II diabetes in humans." (PMID 36139886, 2022). "In conclusion, we found that subjects with RPH proved to be insulin sensitive and demonstrated no biochemical deterioration of beta-cell secretory function or new-onset type 2 diabetes during the observation period." (PMID 36557270, 2022). "In contrast, plasma insulin concentrations were significantly higher in the T-carrying group after the ingestion of standard meals in impaired fasting glucose (IFG), impaired glucose tolerance (IGT), and type 2 diabetes participants." (PMID 36155628, 2022).
type 2 diabetes (continued). "The fact that type 1 diabetes does not have the effect of type 2 diabetes highlights the role of insulin sensitivity versus presence/absence of insulin." (PMID 35884888, 2022). "We conducted a post hoc analysis of the MOBILE Study, a multicenter trial examining the impact of CGM versus self-monitoring with a blood glucose meter (BGM) in patients with type 2 diabetes treated with basal insulin without prandial insulin." (PMID 34962151, 2022). "It contains Masoprocol, a lipooxygenase inhibitor as the major antihyperglycemic compound which decreased plasma glucose level in type-2 diabetic mice models without changing the concentration of plasma insulin." (PMID 35282429, 2022). "Type 2 diabetes (T2D) results from the resistance of peripheral tissues (notably liver and muscle) to the actions of insulin due to beta (β)-cell dysfunction and/or increased insulin demands due to obesity." (PMID 35883588, 2022). "Type-2 diabetes mellitus (T2DM) is a chronic metabolic disease characterized by hyperglycemia, in which the body’s metabolism is disrupted as a result of abnormalities in the insulin levels." (PMID 36234759, 2022). "No variation in HbA1c was observed between human insulin and fast-acting insulin analog among the subjects having type-II diabetes." (PMID 35723344, 2022). "Separately, although the regulatory elements implicating SOX4 –a gene involved in insulin secretion–overlapped with a different gene (CDKAL1), this distal locus has indeed previously been studied and found to incriminate SOX4 in the context of type-2 diabetes." (PMID 35316269, 2022). "T2DM, formerly known as non-insulin-dependent or adult-onset diabetes, usually results from the ineffective use of insulin by the body and is estimated to be prevalent in about 95% of people with diabetes." (PMID 36465743, 2022). "People with type 1 diabetes produce very little to no insulin, while those with type 2 diabetes do not efficiently use the insulin their body produce." (PMID 36203526, 2022). "However, we do want to point out that intranasal insulin can improve cerebral blood flow (CBF) in healthy volunteers and those with type 2 diabetes." (PMID 35884888, 2022). "Elevated adipose tissue inflammation and increased cytokine levels are well documented in obesity and type 2 diabetes mellitus (T2DM) and may contribute to both insulin and catecholamine resistance." (PMID 34847077, 2022). "Glucose concentrations in the blood can rise to a level where the kidneys, eyes, nerves, and heart can be damaged, in both Type-1 and Type-2 diabetes, if the body is not provided with insulin." (PMID 36421123, 2022). "A common perception of type 2 diabetes progression is that the IR is countered by increasing insulin secretion until the beta cells in the pancreas can no longer keep up with the insulin demand and die progressively of exhaustion." (PMID 35163806, 2022). "Type I diabetes mellitus is characterized by complete lack of secretion of insulin, while Type II diabetes mellitus is the resistance of peripheral tissues to the action of insulin and inadequate compensatory secretion of insulin." (PMID 35388310, 2022). "The expression of genes that were first shown to be correlated with insulin exocytosis in non-diabetic donors was subsequently assessed in donors with type 2 diabetes." (PMID 35482056, 2022). "Type-2 diabetes mellitus (T2DM) has been accounted for with oxidation impedance, diminished mitochondrial content, hereditary factors, impaired and diminished insulin discharge from beta cells, lower rates of oxidative phosphorylation, and the advancement of unreasonable ROS." (PMID 35568318, 2022). "The Watt laboratory has identified an additional mechanism of ceramide accrual in muscle in type 2 diabetic patients, involving LDL-mediated transport of ceramides and uptake by myotubes, which is sufficient to induce systemic insulin resistance by mediating decreased insulin action in muscle." (PMID 35789435, 2022).